SIRT2 (sirtuin 2)
Diseases named in the same sentence as SIRT2 in open-access papers (continued):
Sharing a sentence is not in itself a finding about the gene and the disease.
cardiac hypertrophy (continued). "Since a reduction in SIRT2 levels led to protection against the development of HF and cardiac hypertrophy, we next studied whether pharmacological inhibition of SIRT2 also exerts protective effects in the heart in response to PO." (PMID 37728319, 2023). "In cardiac hypertrophy, SIRT2 acts as a cardioprotective deacetylase." (PMID 36101744, 2022). "SIRT2 can bind to NFATc2 and deacetylate it, inhibit NFATc2’s activity and then inhibit this signal transduction pathway and inhibit the occurrence of pathological myocardial hypertrophy." (PMID 34028177, 2021). "Therefore, finding a highly effective SIRT2 agonist can effectively suppress the occurrence and development of pathological myocardial hypertrophy and then avoid the development of heart failure." (PMID 34028177, 2021). "In addition, the deacetylation of FOXO1 and PGC1‐α under the influence of SIRT2 is also related to pathological myocardial hypertrophy." (PMID 34028177, 2021). "Therefore, it is reasonable to believe that in the protective effect of SIRT2 on pathological cardiac hypertrophy, LKB1‐AMPK signalling pathway plays a vital role." (PMID 34028177, 2021). "SIRT2 can effectively inhibit pathological cardiac hypertrophy." (PMID 34028177, 2021). "In short, for pathological myocardial hypertrophy, the role of SIRT2 is positive." (PMID 34028177, 2021). "Therefore, our findings demonstrated that PHF19 promoted the development of cardiac hypertrophy via epigenetically regulating SIRT2." (PMID 33611744, 2021). "During cardiac hypertrophy, the level of Sirt2 was decreased in the heart tissues." (PMID 33611744, 2021). "Furthermore, treatment of GSK3 inhibitors attenuate the beneficial effects of SIRT2 overexpression, indicating the importance of GSK3 in SIRT2-mediated regulation of cardiac hypertrophy." (PMID 29504933, 2018). "It is possible that SIRT2 might have multiple and redundant targets to regulate cardiac hypertrophy, as observed in members of sirtuin family (Martínez-Redondo and Vaquero, 2013)." (PMID 29504933, 2018). "In addition, SIRT2 regulates nuclear envelope dynamics, cardiac hypertrophy, metabolism and stress-induced cell death." (PMID 29504933, 2018). "However, Sirt2-KO markedly exaggerated cardiac hypertrophy and fibrosis as well as decreases in cardiac ejection fraction and fractional shortening in aged (24-month-old) mice and Ang II-infused mice, which suggests a contradiction with the fact that SIRT2 helps SMAD2/3 activation." (PMID 37777567, 2023). "Loss of SIRT2 reduces AMP-activated protein kinase (AMPK) activation, promotes aging-related and Ang II-induced cardiac hypertrophy, which indicates that SIRT2 could be a potential target for therapeutic interventions in aging- and stress-induced cardiac hypertrophy." (PMID 35574497, 2022). "Sirt2 is essential for AMPK activation, which limits myocardial hypertrophy brought on by age and Ang II." (PMID 41567643, 2025). "SIRT2 and SIRT4 have been shown to have deleterious effects on ischemia–reperfusion injury and cardiac hypertrophy, respectively." (PMID 41276460, 2025). "Circ_0018553 affects the expression of sirtuin 2 (SIRT2) by acting as a sponge for miR‐4731, thereby inhibiting the process of myocardial hypertrophy." (PMID 39239069, 2024). "Our data indicate that targeting SIRT2 with AGK2 would improve cardiac remodeling and cardiac hypertrophy in response to PO, potentially providing a novel therapy for these disorders." (PMID 37728319, 2023). "Some other targets of SIRT2, such as FOXO1 and PGC1-α, are also known regulators of cardiac hypertrophy." (PMID 36101744, 2022). "However, the upstream regulators of SIRT2 expression during cardiac hypertrophy remain unknown." (PMID 33611744, 2021).
cardiac hypertrophy (continued). "In addition, SIRT2 and SIRT6 have emerged as prominent cardioprotective SIRTs, as deficiency of SIRT2 intensified cardiac hypertrophy in aged mice and mice stressed with angiotensin II, while a loss of SIRT6 in mice resulted in the development of cardiac hypertrophy and HF." (PMID 32486488, 2020). "A recent work suggests that SIRT2 deacetylates LKB1 to promote AMPK activity and regulates the development of cardiac hypertrophy." (PMID 29504933, 2018). "In cardiomyocytes, SIRT2 overexpression reduces ISO-induced protein synthesis, cardiac myocyte size and the expression of ANP, a fetal gene that is considered as a marker of cardiac hypertrophy." (PMID 29504933, 2018). "Finally, our results provide a potential therapy for cardiac hypertrophy by using AGK2, a specific inhibitor of SIRT2." (PMID 37728319, 2023). "The role of the only sirtuin that resides in the cytoplasm, SIRT2, in the development of ischemic injury and cardiac hypertrophy is not known." (PMID 37728319, 2023). "In addition, SIRT2, SIRT5, and SIRT7 have protective effects on cardiac hypertrophy, while SIRT4 appears to have the opposite effect." (PMID 36581622, 2022). "There was evidence that SIRT2 is related to pathological myocardial hypertrophy and plays a negative role in regulating the occurrence and development of pathological myocardial hypertrophy, thereby reducing the severity of illness and heart failure." (PMID 34028177, 2021). "To understand the contribution of GSK3 as a key molecule in the anti-hypertrophic signaling regulated by SIRT2, we treated SIRT2 overexpressing cardiomyocytes with GSK3 inhibitors, LiCl and GSK3 inhibitor X and studied the ISO-induced cardiac hypertrophy." (PMID 29504933, 2018). "Although multiple sirtuins have been investigated in the context of cardiovascular diseases, it is not known whether SIRT2 has a role in protection against HF and cardiac hypertrophy." (PMID 37728319, 2023). "Furthermore, SIRT2 and SIRT5 might also have protective effects on cardiac hypertrophy and fibrosis." (PMID 36581622, 2022). "Moreover, deletion of SIRT2 exacerbates cardiac hypertrophy and fibrosis and decreases cardiac ejection fraction and fractional shortening in angiotensin II-infused mice by inhibition of AMPK activation, whereas cardiac-specific SIRT2 overexpression reversed this phenotype." (PMID 36009379, 2022).
Insulin resistance (36 papers, 2017 to 2025). Increased resistance towards insulin, that is, diminished effectiveness of insulin in reducing blood glucose levels. "The report also indicated that liver-specific Sirt2 deficiency promoted insulin resistance, hepatic steatosis, and inflammation, while liver-specific Sirt2 overexpression reversed metabolic dysfunction." (PMID 39004743, 2024). "More recently, in the context of HIV infection, the potential roles of SIRT2 in some HIV-associated comorbidities (insulin resistance and cardiovascular diseases), but also with neurocognitive disorders and virus life cycle, have emerged." (PMID 36719240, 2023). "A recent study has demonstrated that SIRT2 is necessary and beneficial for preventing aging and overnutrition-associated chronic inflammation and insulin resistance." (PMID 37698780, 2023). "Thus, SIRT2 deficiency in mice leads to impaired glucose homeostasis and exacerbates insulin resistance under obesogenic conditions." (PMID 35743232, 2022). "Moreover, hepatocyte-specific SIRT2 deficiency in mice aggravates HFD-induced insulin resistance, glucose intolerance, and hepatic steatosis and associated inflammatory markers." (PMID 35743232, 2022). "Moreover, they show that NLRP3 deacetylation by SIRT2 regulates aging-associated inflammation and insulin resistance." (PMID 33803627, 2021). "The present findings support the paradigm that weight gain, inflammation and insulin resistance are closely linked in liver and raise the possibility that the presence of SIRT2 may be protective to this process." (PMID 30533032, 2018). "However, SIRT2 has been linked with metabolic syndrome/insulin resistance under different challenges." (PMID 28984064, 2017). "The upregulation of SIRT2 expression improves insulin resistance, cell apoptosis, and cardiac dysfunction, mainly by deacetylating and disrupting CPT2 expression." (PMID 39781464, 2025). "Restoring hepatic SIRT2 mitigated insulin resistance, hepatic steatosis, and inflammation, while liver-specific ablation exacerbated dysfunctions." (PMID 40076884, 2025). "Cardiac-specific overexpression of SIRT2 protected mice from streptozotocin/high-fat diet (STZ/HFD)-induced insulin resistance (IR), cell apoptosis, and cardiac dysfunction, whereas its downregulation exacerbated these conditions." (PMID 39781464, 2025). "We found that glucose tolerance and insulin resistance were gradually restored following Sirt2 injection in the knockout mice, and liver MRI results showed no abnormal liver morphology in the second group of mice." (PMID 39004743, 2024). "Lantier also showed that severe insulin resistance occurred in the liver of Sirt2 knockout rats fed a high-fat diet." (PMID 39004743, 2024). "For example, SIRT2 deacetylates NLRP3 in macrophages and inactivates the NLRP3 inflammasome, which functions to reverse aging-associated inflammation and insulin resistance." (PMID 39372420, 2024). "Together, these results suggested that Sirt2 deletion affected liver function and that mice developed insulin resistance and induced reprogramming of glucose metabolism." (PMID 39004743, 2024). "Conversely, SIRT2 deletion induces muscle insulin resistance, while inhibiting SIRT2 improves insulin sensitivity in insulin-resistant muscle cells 28,140." (PMID 38904020, 2024). "Regarding NLRs, sirtuin 2 (SIRT2) deacetylates NLRP3, preventing age-related inflammation and insulin resistance, which can be reversed by NLRP3 K21/22/24R mutations." (PMID 38970666, 2024). "SIRT2 plays a vital role in supporting insulin resistance, and downregulation of SIRT2 improves insulin sensitivity." (PMID 36815979, 2023). "Co‐culture of SIRT2 overexpressing macrophages with aged WT adipose tissue reduced insulin resistance, but the only read out for this is Akt phosphorylation which does not reflect actual insulin action, as mediated by GLUT4 translocation." (PMID 38009412, 2023).
Insulin resistance (continued). "SIRT2 and NLRP3 deacetylation prevent and can be targeted to reverse, aging‐associated inflammation, and insulin resistance." (PMID 37143582, 2023). "NLRP3 is modified and activated by acetylation in macrophages and is deacetylated by Sirtuin 2 (SIRT2), a cytosolic NAD+-dependent deacetylase and metabolic sensor, contributing to aging-associated inflammation and insulin resistance." (PMID 34157289, 2021). "SIRT2 is also described as a novel AKT interactor, critical for AKT activation by insulin, and the potential usefulness of SIRT2 activators in the treatment of insulin-resistant metabolic disorders has been discussed." (PMID 33639916, 2021). "In this context, SIRT2 overexpression in old macrophages reduced NLRP3 acetylation and activation, reversing aging-associated insulin resistance and neuroinflammation." (PMID 33803627, 2021). "Knockdown of SIRT2 contributed to liver insulin resistance in mice, and increased food intake in response to high-fat diet." (PMID 32781630, 2020). "Among these, SIRT1 and SIRT2 were known as class I in sirtuin family, which exerted diverse influence on lifespan, insulin resistance, and metabolism." (PMID 32781630, 2020). "As a highly conserved NAD+-dependent histone deacetylase, SIRT2 participates in many metabolic processes, such as oxidative stress, mitochondrial efficacy, and insulin resistance." (PMID 32438712, 2020). "For instance, deacetylation of NLRP3 by SIRT2 reduces IL-1β production in macrophages, and hence improves aging-related inflammation and insulin resistance in rodents." (PMID 32545355, 2020). "Although SIRT2 deletion is sufficient to induce muscle insulin resistance, this impairment is offset by effects on other tissues, so that it is undetectable by techniques used to study the whole body." (PMID 30533032, 2018). "The weight-matched subgroup did not exhibit significantly different GIR between HF-fed WT and SIRT2 KO mice, suggesting that the additional weight gain was required for the whole-body insulin resistance in the HF-fed SIRT2 KO mice." (PMID 30533032, 2018). "In conclusion, the present study shows that whole body SIRT2 KO leads to widespread metabolic defects that include increased energy intake, adiposity, and insulin resistance in mice on a HF diet." (PMID 30533032, 2018). "This indicates that the liver insulin resistance in HF-fed SIRT2 mice was attributable to increased body mass." (PMID 30533032, 2018). "In summary, SIRT2 deletion in vivo reduces muscle insulin sensitivity and contributes to liver insulin resistance by a mechanism that is unrelated to cytosolic acetylation state." (PMID 30533032, 2018). "In skeleton muscles, SIRT2 acts as a key component of a signaling network required to maintain the status of insulin resistance and down-regulation of SIRT2 improves insulin sensitivity." (PMID 27659520, 2017). "Moreover, using AAV-mediated delivery of cardiac SIRT2 into STZ/HFD-induced diabetic mice, we observed that SIRT2 overexpression significantly alleviated type II diabetes-related insulin resistance, cell apoptosis, and cardiac dysfunction." (PMID 39781464, 2025). "However, on the other hand, in the periphery, SIRT2 levels are reduced with aging while keeping its expression is protective against age-related peripheral inflammation, insulin resistance, and cardiovascular diseases." (PMID 38132302, 2023). "In addition, a recent study has shown that SIRT2 prevents and reverses age-related inflammation and insulin resistance." (PMID 37698780, 2023). "Authors hypothesize that SIRT2 is necessary for glucose homeostasis and prevents aging-related inflammation and insulin resistance." (PMID 37698780, 2023). "In addition, they demonstrate that 2-year-old SIRT2 KO mice fed a chow diet exhibit metabolic alterations, insulin resistance, and peripheral chronic inflammation." (PMID 38132302, 2023).
Insulin resistance (continued). "Importantly, in our previous study we showed that SIRT2 counteracts insulin resistance in hepatocytes by mitigating oxidative stress and mitochondrial dysfunction, which are common pathogenic events in NAFLD." (PMID 35743232, 2022). "RES could effectively improve insulin resistance and restore the glycolysis pathway by regulating SIRT2, which may contribute to attenuating the ovarian damage of PCOS rats and provide a potential treatment for patients with PCOS." (PMID 36742000, 2022). "Sirtuin 2 is also indicated as an important modulator of insulin resistance development." (PMID 34685718, 2021). "The major function of SIRT2 in the brain is to regulate insulin resistance by interacting with AKT." (PMID 33806509, 2021). "Knockdown of SIRT2 in insulin-resistant cells ameliorates insulin sensitivity in mouse muscle cells; however, knocking out SIRT2 in mice could exacerbate insulin resistance in muscle cells." (PMID 33806509, 2021). "In addition, SIRT2 expression was positively correlated with body mass index and high density lipoprotein cholesterol in children with obesity and insulin resistance." (PMID 32438712, 2020). "Furthermore, SIRT2 expression in peripheral blood mononuclear cells (PBMCs) from human subjects was negatively correlated with obesity, insulin resistance and oxidative stress." (PMID 30972029, 2019). "Liver insulin resistance in response to HF diet is amplified by SIRT2 KO." (PMID 30533032, 2018). "Lean SIRT2 KO mice exhibited insulin resistance in skeletal muscle." (PMID 30533032, 2018). "SIRT2 negatively regulates insulin resistance and glucose uptake in C2C12 muscle cells." (PMID 30559718, 2018). "Our findings suggest that changes in energy balance (i.e the difference between energy intake and energy expenditure), as opposed to liver protein acetylation, may be the main driver for the liver insulin resistance observed in SIRT2 KO mice." (PMID 30533032, 2018). "We further show that liver insulin resistance in HF-fed mice is worsened by SIRT2 KO." (PMID 30533032, 2018). "Taken together, our results show that SIRT2 deletion, independent of diet and body weight, was sufficient to cause muscle insulin resistance." (PMID 30533032, 2018). "We hypothesized that deletion of SIRT2 would lead to increased acetylation and a more severe insulin resistance when fed a HF diet." (PMID 30533032, 2018). "However, further studies are necessary to elucidate whether this anti-inflammatory effect of SIRT2 may be exerted in metabolic diseases, including insulin resistance and T2DM." (PMID 30972029, 2019). "However, the insulin resistance that accompanies HF-feeding was worsened in SIRT2 KO mice." (PMID 30533032, 2018). "Further, SIRT2 has been shown to be downregulated in visceral white adipose from obese subjects as well as liver from ob/ob mice, suggesting SIRT2 may play an important role in the development of insulin resistance." (PMID 30533032, 2018). "SIRT2 overexpression decreased CPT2 protein expression and promoted insulin resistance, cell apoptosis, and cardiac dysfunction both in vivo and in vitro." (PMID 39781464, 2025). "In T2DM, Sirt2 overexpression significantly enhances the activation of AKT and its downstream targets involved in insulin resistance." (PMID 39004743, 2024). "Sirtuins, including SIRT1, SIRT2, SIRT3, and SIRT6, play crucial roles in regulating cellular metabolism, and their dysregulation contributes to insulin resistance and diabetes, notably affecting skeletal muscle." (PMID 38904020, 2024). "HFD feeding promoted insulin resistance in both genotypes when evaluated by HOMA-IR or ITT; however, SIRT2-KO mice were significantly more insulin resistant than WT mice." (PMID 35743232, 2022). "Although apparently normal under a control diet, SIRT2-KO mice showed accelerated body weight gain and adiposity on a HFD, accompanied by severe insulin resistance." (PMID 35743232, 2022).